ENO1 (enolase 1)
Diseases named in the same sentence as ENO1 in open-access papers (continued):
Sharing a sentence is not in itself a finding about the gene and the disease.
ovarian carcinoma (17 papers, 2011 to 2025). A malignant neoplasm originating from the surface ovarian epithelium. "In particular, HPD binding is demonstrated to mediate translation of glycolytic enzymes triosephosphate isomerase (TPI) and alpha‐enolase (ENO1) mRNAs, which facilitates ovarian cancer glycolysis and tumor growth." (PMID 40491422, 2025). "In summary, HPD is positively correlated with the protein levels of TPI and ENO1, which play an important role in the progression of ovarian cancer." (PMID 40491422, 2025). "In the present study, we found that targeting PRMT5 activity by using DW14761 significantly suppressed ovarian cancer growth by regulating glycolysis through methylating ENO1." (PMID 36999124, 2023). "In this study, we identified an increased expression of pyruvate kinase M1/2, enolase 1, and aldolase, fructose-bisphosphate A, in circulating extracellular vesicles of patients with ovarian cancer recurrence compared to the controls." (PMID 34298602, 2021). "The expression of pyruvate kinase M1/2, enolase 1, and aldolase fructose-bisphosphate were significantly higher in circulating sEVs of patients with ovarian cancer recurrence compared to the controls." (PMID 34298602, 2021). "ENO1 has been observed to co-precipitate with uPAR in a multi-protein complex in ovarian cancer cells." (PMID 23894455, 2013). "Furthermore, HPD increases the translation level of glycolytic enzymes, TPI and ENO1, to promote the progression of ovarian cancer." (PMID 40491422, 2025). "In addition, NTBC inhibited the proliferation of ovarian cancer cells and down‐regulated the protein levels of TPI and ENO1 in ovarian cancer cells." (PMID 40491422, 2025). "To test this hypothesis, we first knocked down ENO1 in ovarian cancer cells with shRNA and found that the depletion of ENO1 inhibits cell proliferation and reduces lactate production in ovarian cancer cells." (PMID 36999124, 2023). "Thus, we first reported that PRMT5 enhances glycolysis in ovarian cancer by interacting with and methylating ENO1." (PMID 36999124, 2023). "Together, our data reveal a novel role of PRMT5 in promoting ovarian cancer growth by controlling glycolysis flux mediated by methylating ENO1, and highlights that PRMT5 may represent a promising therapeutic target for treating ovarian cancer." (PMID 36999124, 2023). "In addition, we demonstrated that PRMT5 is a critical enzyme for ENO1 arginine symmetric dimethylation modification and enhance its activity, which regulates glycolysis pathway, and promotes ovarian cancer growth." (PMID 36999124, 2023). "Furthermore, the combination of citrullinated VIM and ENO1 peptides in a vaccine, designated Modi-1, induced a significant antitumoral response in a mouse model of ovarian cancer." (PMID 36291752, 2022). "In addition to ovarian cancer, T cell responses targeting ENO1 have also been reported in patients with PDA." (PMID 33584813, 2020). "However, the role of symmetric dimethyl arginine (SDMA) modifications on ENO1 in regulating cell metabolism, tumor growth, and chemotherapy responses of ovarian cancer remains largely unknown." (PMID 36999124, 2023). "Similarly, low expression of ENO1 could regulate pancreatic ductal adenocarcinoma and ovarian cancer by inducing tumor cell senescence." (PMID 34504528, 2021). "We collected 20 normal ovarian tissues and 20 ovarian cancer tissues, and detected the protein levels of HPD, TPI, and ENO1 by WB." (PMID 40491422, 2025). "In endometrial and ovarian cancers, the expression of TPI-1 and ENO1 was higher in metastatic tumors than in primary tumors; this finding was consistent with the reported role of these proteins in promoting tumor cell survival and proliferation." (PMID 23504277, 2013). "Finally, NTBC inhibited the development of ovarian cancer in A2780 CDX mouse model and reduced the protein levels of TPI and ENO1." (PMID 40491422, 2025).
ovarian carcinoma (continued). "Furthermore, as the protein level of HPD increases in ovarian cancer cell lines, so does the protein level of TPI and ENO1." (PMID 40491422, 2025). "More importantly, we found that the protein levels of TPI and ENO1 were positively correlated with HPD in ovarian cancer tissues, but not in normal ovarian tissues." (PMID 40491422, 2025). "Given that HPD controls translation regulation of ENO1 and TPI, we next wanted to find out whether ENO1 and TPI are involved in glycolysis and cell proliferation in HPD‐mediated RBP‐dependent manner in human ovarian cancer." (PMID 40491422, 2025). "Given that HPD controls translation regulation of TPI and ENO1, we next wanted to find out whether TPI and ENO1 are co‐expressed with HPD in human ovarian cancer." (PMID 40491422, 2025). "In the current study, we surprisingly demonstrate that HPD works as an RBP to promote ovarian cancer glycolysis flux by increasing global mRNA translation, including glycolytic metabolic enzymes TPI and ENO1, thereby promoting the tumorigenesis of ovarian cancer." (PMID 40491422, 2025). "PRMT5 promotes ovarian cancer growth and Taxol response through enhancing glycolysis pathway, which mediated by regulating the symmetric dimethylation of arginine (SDMA) modification of ENO1." (PMID 36999124, 2023). "In terms of mRNAs, one study based on Gene Expression Omnibus (GEO) and The Cancer Genome Atlas (TCGA) databases demonstrates the positive correlations between ovarian cancer biomarkers (such as CD44) and glycolytic biomarkers (such as hexokinase 2 (HK2), lactate dehydrogenase A (LDHA), and ENO1)." (PMID 35498135, 2022). "By assessing the T cell repertoire to citrullinated peptides in ovarian cancer patients and healthy donors, it was demonstrated that PBMC from 58% of patients proliferated in response to at least one of the PTM peptides and only 12% to both citrullinated Vim and ENO1 peptides." (PMID 36612133, 2022). "Serous ovarian cancer cell lines OVCA420 and OVCA429 were growth inhibited in hypoxia (1% O2) and glucose deprivation (HG) conditions and the transfection with siRNA targeting HIF1 α and ENO1 has limited effect on further growth inhibition compared to the control transfected cells." (PMID 21754983, 2011). "It is not clear if, like in RA, citrullination triggers ENO1 autoantibodies in cancer patients, although citrullinated ENO1 was reported to elicit anti-tumor CD4+ T responses in murine tumor xenografts and in ovarian cancer patients." (PMID 33584813, 2020).
head and neck cancer (16 papers, 2011 to 2025). A primary or metastatic malignant neoplasm affecting the head and neck. "Furthermore, ENO1 is a prognostic marker in the HPV-associated head and neck cancer, and it was recently shown that ENO1 silencing impairs cancer cell line growth." (PMID 28670312, 2017). "The ENO1 was also highly expressed in metastatic head and neck cancer cells, and the roles of ENO1 in head and neck cancer and oral squamous cell carcinoma have also been reported in promoting the occurrence and enhancing the lymphatic invasion." (PMID 36361568, 2022). "A previous study showed that ENO1 was overexpressed in head and neck cancer cells, highly expressed in patients with cervical lymphatic metastasis, and closely related to poor clinical outcomes." (PMID 36361568, 2022). "In head and neck cancer, patients with elevated expression of ENO1 suffered from worse clinical outcome including shorter overall and progression-free survival than those with lower expression." (PMID 29483925, 2018).
prostate carcinoma (15 papers, 2013 to 2025). A carcinoma that arises from epithelial cells of the prostate gland. "This indicates a role for ENO1 in the progression of prostate cancer via the promotion of migration." (PMID 40214422, 2025). "Mechanistically, ECM1 interacts with the enolase 1 (ENO1) receptor on the prostate cancer cell membrane, leading to its phosphorylation at the Y189 site." (PMID 39563492, 2025). "One exemplar protein of this metabolic pathway enrichment, enolase 1 (ENO1), converts 2-phosphoglycerate to phosphoenolpyruvate and serves as a cell surface receptor for plasminogen, where it is potentially involved in prostate cancer cell migration." (PMID 39125581, 2024). "For example, estrogen promotes cell migration via the paracrine release of ENO1 from stromal cells in prostate cancer." (PMID 32013122, 2020). "Several studies have shown that ENO1 is overexpressed in many types of cancer, including breast, lung, and prostate cancers." (PMID 32013122, 2020). "In public datasets, there was positive expression correlation between CUX1 and ENO1, GPI, or PGK1 in NB, colon cancer, or prostate cancer tissues, and their levels were associated with poor survival of tumor patients." (PMID 31709724, 2019). "Through a MALDI-TOF analysis of conditioned media, secreted enolase 1 (ENO1) was identified and shown to be the factor responsible for increased cell migration, acting at the surface of prostate cancer cells to promote plasminogen activation." (PMID 24713112, 2014). "Identification of exosomal proteins using high performance LC-FTMS resulted in the discovery of PDCD6IP, FASN, XPO1 and ENO1 as new candidate biomarkers for prostate cancer." (PMID 24391718, 2013). "Additionally, the findings indicate that ECM1 and ENO1 may serve as potential targets for developing therapies for bone metastatic castration‐resistant prostate cancer." (PMID 39563492, 2025). "Analysis indicated that the 9 hub genes (AKT1, HSP90AA1, SRC, GSK3β, VEGFR2, RHOA, ENO1, PKM, and IL-2) play roles in MF treatment by participating in signaling pathways related to prostate cancer, lipid and atherosclerosis, and insulin resistance." (PMID 40051434, 2025). "In another study, inhibition of ENO1 by HuL227 halted inflammation-induced migration of PC-3 prostate cancer cells and reduced CCL2 or TGFβ-enhanced migration of PC-3 and DU145 prostate cancer cells." (PMID 40214422, 2025).
liver cancer (14 papers, 2017 to 2025). An epithelial or non-epithelial malignant neoplasm that arises from the liver. "Previous studies have shown that ENO1 promotes the development of liver cancer by binding to the YAP and IRP 1 mRNAs." (PMID 41208958, 2025). "PP inhibits the protein expression of ENO1 and AKT, and the production of CyclinE1 downstream of the PI3K/AKT pathway is associated with the growth and movement of liver cancer cells." (PMID 39576845, 2024). "This demonstrates that inhibition of ENO1 can inhibit the proliferation of liver cancer cells from another aspect." (PMID 39576845, 2024). "This study provides evidence that the combination of GRN A and cisplatin is able to sensitize the liver cancer to cisplatin, and that targeting ENO1 is a promising approach for enhancing the antitumor activity of cisplatin." (PMID 30301274, 2018). "Measured in initial tissues, the S27 site of ENO1 exhibits the most types of cancer with different phosphorylation levels in all primary tumor tissues and the most significant difference in the phosphorylation levels of liver cancer cells." (PMID 39576845, 2024). "Furthermore, 1000 lasso analysis also identified five genes: ADH4, AKR1B10, CEBPZOS, ENO1, and FOXN2, as the most stable prognosis-related genes associated with energy metabolism in liver cancer." (PMID 35602603, 2022). "In addition, ENO1 is highly expressed in liver cancer, promotes glucose uptake and lactate production by tumor cells, and is involved in tumor cell division, proliferation, apoptosis, metastasis, immunomodulation, and chemoresistance." (PMID 35602603, 2022). "In addition, the HIF1α-related gene ENO1 can bind and degrade the expression of the hepcidin gene, thereby regulating the metabolic homeostasis of intracellular iron ions, affecting ferroptosis, and promoting the occurrence and development of liver cancer." (PMID 35860430, 2022). "Moreover, the results of the present study showed that HOXA3 might interact with TRIM29, ENO1 and SFN, which was reportedly associated with the occurrence of liver cancer." (PMID 33683826, 2021). "Based on the marker genes of this cluster and TCGA database data, the five most stable key genes (ADH4, AKR1B10, CEBPZOS, ENO1, and FOXN2) were identified as energy metabolism-related genes in liver cancer." (PMID 35602603, 2022). "However, enolase 1, an RNA-binding protein, binds and stabilizes YAP1 mRNA to promote liver cancer by activating arachidonic acid metabolism in cells." (PMID 40302792, 2025). "It is conjectured that ENO1 acts as an upstream molecule in the PI3K/AKT pathway, and suppressing ENO1 can reduce the activation of the PI3K/AKT pathway and hinder the growth and spread of SK-Hep-1 liver cancer cells." (PMID 39576845, 2024).
colon cancer (13 papers, 2008 to 2025). "ENO1 overexpression in colon cancer tissues is associated with disease progression." (PMID 39513918, 2024). "Enolase-1 acts as a central element in colon cancer susceptibility and protein biosynthesis." (PMID 23845056, 2013). "This study demonstrated that IL8, DES and ENO1 act as the central elements in colon cancer susceptibility, and protein biosynthesis and the ribosome-associated function categories largely account for the colon cancer tumuorigenesis." (PMID 18691435, 2008). "As anticipated, the ubiquitylation level of ENO1 was distinctly decreased in CD47-overexpressed HT29 colon cancer cells but increased in CD47-knockdown HT29 cells." (PMID 32226539, 2020). "Additionally, our identification of RNF8-interacting ENO1, LDH1, PKM, PYCR, and MDH2 might provide other mechanisms underlying RNF8-regulated colon cancer progression." (PMID 35831895, 2022). "In colon cancer, FBXW7 inhibits enolase 1 activity via the ubiquitin/proteasome pathway in a glycogen synthase kinase 3-dependent manner." (PMID 39823500, 2025). "ENOblock, a small molecule nonsubstrate analogue that inhibits ENO1, was shown to suppress colon cancer cell metastasis and induce cellular glucose uptake." (PMID 31889896, 2019). "Further analysis of the topological architectures of the network identified three known hub cancer genes (IL8; DES and ENO1), while two novel hub genes (RBM9 and RPL30) may define new central elements in the gene network specific to colon cancer." (PMID 18691435, 2008).
neuroblastoma (13 papers, 2005 to 2022). Neuroblastoma (NB) is the most common solid, extracranial childhood tumor. "Here we demonstrate that transfection of ENO1 cDNA into 1p-deleted neuroblastoma cell lines causes' reduced number of viable cells over time compared to a negative control and that it induces apoptosis." (PMID 16359544, 2005). "Enolase-1 is ubiquitously expressed in adult tissues including the brain and liver and elevated in neuroblastoma." (PMID 27115744, 2016). "The over expression of ENO1 has been shown to inhibits cell growth and induce apoptosis in neuroblastoma cells." (PMID 18430238, 2008). "Although small numbers (11 primary neuroblastomas), there is some evidence that Stage 4 tumours has a lower level of ENO1-mRNA than Stage 2 tumours (p = 0.01)." (PMID 16359544, 2005). "We conclude that over-expression of ENO1 has the same effect in both neuroblastoma cells and transformed kidney cells, and that ENO1 can function as a general tumour suppressor." (PMID 16359544, 2005). "The DNA transfection studies also showed that the ENO1 gene did have the strongest and most consistent effect (approximately 20% reduction) on the growth rate of 1p-deleted neuroblastoma cells (SK-N-AS and IMR32) compared to an empty vector control." (PMID 16359544, 2005). "We were in fact able to identify one gene, ENO1, located in the smallest region of overlap of deletion in neuroblastoma, which did seem to have tumour suppressor activity." (PMID 16359544, 2005). "After transfection of ENO1 into the 293 cells the same results were obtained as with the neuroblastoma cell lines, that is, the number of viable cells over time was reduced by 20–40 %." (PMID 16359544, 2005). "Effects of in vitro transcribed ENO1 mRNA constructs on cell growth after transfection into neuroblastoma (SK-N-AS), 293 and K562 cell lines." (PMID 16359544, 2005). "Our studies demonstrate that ENO1 overexpression in both neuroblastoma and 293 cells significantly reduces cell growth and induces apoptosis, implicating ENO1 in tumourigenesis." (PMID 16359544, 2005). "The α-enolase (ENO1) gene is located in chromosome region 1p36.2, within the common region of deletion in neuroblastoma." (PMID 16359544, 2005). "In conclusion, our studies demonstrate that ENO1, a gene mapping to a region commonly deleted in advanced neuroblastoma tumours, can act as a strong tumour suppressor by slowing down the cell growth and inducing apoptosis." (PMID 16359544, 2005). "In neuroblastoma, the upregulation of ENO1 expression can inhibit cell proliferation and induce apoptosis, and the ENO1 gene has a strong dose-dependent inhibitory effect on the growth of tumor cells, indicating that the significance of ENO1 is varied in different types of tumor cells." (PMID 35434271, 2022). "Studies on neuroblastoma seem to rule out that mutations inactivating the ENO1 gene are involved in controlling MBP-1 expression." (PMID 20886042, 2010). "Interestingly, a similar but much stronger dose-dependent reduction of cell growth was observed by transfection of in vitro transcribed ENO1 mRNA into neuroblastoma cells." (PMID 16359544, 2005). "The mutation screening of the promoter region and of all exonic sequences of ENO1, including exon/intron boundaries, and of introns 5–7 in 48 primary neuroblastoma samples of different stages did not reveal any mutations (data not shown)." (PMID 16359544, 2005). "Real time-PCR studies of the ENO1 gene on cDNA-samples showed a 55% reduction (p = 0.01) of ENO1-mRNA levels in stage 4 neuroblastoma tumours compared to stage 2 tumour levels (average relative concentration of 0.5 in stage 2 tumours compared to 0.23 in stage 4 tumours)." (PMID 16359544, 2005). "We could show that ENO1 mRNA has a strong, dose dependent, inhibitory effect on cell growth in neuroblastoma cells (SK-N-AS)." (PMID 16359544, 2005).
neuroblastoma (continued). "In order to see whether ENO1 was equally expressed in both low stage and advanced neuroblastomas, and also to compare this with the mRNA-levels in neuroblastoma cell lines, we conducted a real-time-PCR-study using Taqman." (PMID 16359544, 2005). "This indicates that ENO1 acts in a dose dependent manner, suggesting that cellular levels of ENO1 might play a crucial role in regulating apoptosis and proliferation in neuroblastoma cells." (PMID 16359544, 2005). "TUNEL staining, followed by FACS-analysis, of ENO1-transfected SK-N-AS neuroblastoma cells two days after transfection showed a higher degree of apoptotic cells (59%) than with the empty vector control (9%) or any of the other constructs tested (8–26% apoptotic cells)." (PMID 16359544, 2005). "Even though small sample number (11 primary tumours), we could detect a difference (p = 0.01) in the levels of ENO1-mRNA in Stage 4 neuroblastomas compared to Stage 2 neuroblastomas." (PMID 16359544, 2005). "Deletion of the 1p chromosomal region is obviously one way to achieve a reduction in expression of ENO1, but it is not clear whether a reduction in the expression of the second allele is also necessary through other mechanisms in neuroblastoma." (PMID 16359544, 2005). "In this paper we have functionally screened six candidate genes from the 1p36.2 region (CORT, DFFA, ENO1, ICAT, PEX14 and PGD) in neuroblastoma cells." (PMID 16359544, 2005).